COMT (catechol-O-methyltransferase)
Diseases named in the same sentence as COMT in open-access papers (continued):
Sharing a sentence is not in itself a finding about the gene and the disease.
Intellectual disability (2 papers, 2019 to 2022). "Genetic variants of DCX, COMT and FMR1 have been linked to neurodevelopmental disorders related to intellectual disability and social behavior." (PMID 35590332, 2022). "Taken together our findings indicate that factors connecting DCX, COMT, and FMR1 in intellectual disability and social behavior may converge at Wnt signaling, neuron migration, and axon and dendrite morphogenesis." (PMID 35590332, 2022).
joint disorder (2 papers, 2016 to 2025). "After adjusting for other variables in the multiple regression analysis, TMJ was associated with the rs174675 recessive C COMT polymorphism (p = 0.018), indicating that people without the rs174675 recessive C COMT polymorphism had 82% less chance of presenting joint disorder." (PMID 40435063, 2025).
liver cancer (2 papers, 2016 to 2017). An epithelial or non-epithelial malignant neoplasm that arises from the liver. "We have noted that different liver cancer cell lines responded differently to E2 treatment, hence we examined the expression levels of CYP1A2 and COMT in these cell lines but didn’t get meaningful results to explain the phenomena." (PMID 27093553, 2016).
lumbar disc herniation (2 papers, 2018 to 2020). "Important role of COMT gene in the symptomatic lumbar disc herniation is show in susceptibility studies with the influence of genetic variants of COMT gene in the variation in pain after treatment for low back pain." (PMID 32098249, 2020).
malnutrition (2 papers, 2019 to 2024). Inadequate nutrition resulting from poor diet, malabsorption, or abnormal nutrient distribution. "Specifically malnutrition lowers transcription of the catechol-O-methyltransferase gene in the humans and the prefrontal cortex of male rats which may contribute to altered catecholamine signaling in the cortex of malnourished subjects." (PMID 30853881, 2019).
Myalgia (2 papers, 2021 to 2024). "Myofascial pain with referral and myalgia showed a strong association with the COMT SNPs rs9332377 and rs4646310." (PMID 39457643, 2024). "The distribution of HTR2A (rs9316233), HTR3A (rs1062613), HTR3B (rs1176744), SERT (5-HTTLPR) and COMT (rs4680) genotypes in 117 patients with TMD myalgia (16 men and 101 women)." (PMID 35047998, 2021).
myoma (2 papers, 2021 to 2022). "It has also been reported that vitamin D inhibits uterine myoma cell growth through the downregulation of proliferating cell nuclear antigen and cyclin-dependent kinase 1 and the inhibition of COMT expression and activity." (PMID 33504114, 2021). "Beside apoptosis induction, Vitamin D suppresses catechol-O-methyltransferase (COMT) expression and activity in myoma cells—an enzyme that plays a vital role in myoma formation." (PMID 35215384, 2022).
narcolepsy (2 papers, 2008 to 2020). A sleep disorder characterized by a tendency for excessive sleepiness during the day which occurs even after adequate sleep in the nighttime. "COMT genotype distribution between male and female patients was associated with the response to modafinil in Caucasians, since the optimal dose of modafinil was approximately 100 mg lower in females with narcolepsy, suggesting that females are better responders to the drug." (PMID 18706091, 2008). "Females with narcolepsy with high COMT activity fell asleep twice as fast as those with low COMT activity during the multiple sleep latency test, while the opposite was true for men." (PMID 18706091, 2008).
opiate dependence (2 papers, 2011 to 2022). Disorders related or resulting from abuse or mis-use of opioids. "There are few studies on the potential relationship between opioid dependence and COMT Val108/158Met polymorphism." (PMID 36292653, 2022).
Oppositional defiant disorder (2 papers, 2009 to 2019). An enduring pattern of uncooperative, defiant, and hostile behavior towards authority figures that does not involve major antisocial violations, is not accounted for by the child's developmental stage, and results in significant functional impairment. "Our study of attention deficit hyperactivity disorder comorbid oppositional defiant disorder and its predominately inattentive type highlights the potential etiologic role of COMT for ADHD children in China." (PMID 19228412, 2009).
orthostatic hypotension (2 papers, 2019 to 2023). Sudden fall of the blood pressure of at least 20/10 mm Hg when a person stands up. "Other drug strategies, like dopamine agonists and catechol-O-methyltransferase inhibitors, have non-motor side effects such as hallucinations, constipation, and orthostatic hypotension." (PMID 37840914, 2023).
pancreatic adenocarcinoma (2 papers, 2013 to 2023). "According to our observations, [18F]FDOPA combined with [18F]FDG imaging is a useful tool for detecting pancreatic adenocarcinoma, either alone or with COMT + MAO-A pretreatment, but not with carbidopa pretreatment." (PMID 23497589, 2013). "COMT was highly expressed in 3 tumor types (KIPAN, uveal melanoma [UVM], pancreatic adenocarcinoma [PAAD]) with poor prognosis and poorly expressed in 2 tumor types (GBMLGG, pheochromocytomas, and paragangliomas [PCPG]) with poor prognosis." (PMID 37564635, 2023).
personality disorder (2 papers, 2021 to 2025). A diverse category of psychiatric disorders characterized by behavior that deviates markedly from the expectations of the individual's culture; this pattern of deviation is pervasive and inflexible and is stable over time. "Further research is needed to confirm the association between COMT rs4680 and rs4818 polymorphisms and the risk of psychopathy-related behaviors in youth, adults, male and female populations, and in different ethnicities, but also in other personality disorders." (PMID 40305338, 2025).
polyneuropathy (2 papers, 2022 to 2024). A disease or disorder affecting more than one nerve. "It is suggested that levodopa methylation by COMT increases the homocysteine levels which among other metabolites may cause polyneuropathy." (PMID 38386490, 2024). "Consequently, it is proposed that the COMT inhibitor may have a protective role against polyneuropathy." (PMID 38386490, 2024).
Premature ovarian insufficiency (2 papers, 2014 to 2019). Amenorrhea due to loss of ovarian function before the age of 40. "We were able to demonstrate a strong association between the COMT Val/Met polymorphism and the risk of premature ovarian insufficiency in the Brazilian women evaluated." (PMID 24808926, 2014).
renal carcinoma (2 papers, 2015 to 2021). A carcinoma arising from the epithelium of the renal parenchyma or the renal pelvis. "In 4-hydroxyestradiol stimulated renal cancer cells, COMT caused increased apoptosis along with increased GADD45a levels." (PMID 34587154, 2021). "The polymorphisms of catechol-O-methyltransferase in men were associated with renal cancer." (PMID 26537097, 2015). "This tumor suppressive effect of COMT is also shown in other cancers such as pancreatic and colorectal; and in a prior study done in our laboratory, COMT significantly reduced proliferation of renal cancer cells treated with 4-hydroxyestradiol as compared to vector control." (PMID 34587154, 2021).
vitiligo (2 papers, 2014 to 2021). Generalized well circumscribed patches of leukoderma that are generally distributed over symmetric body locations and is due to autoimmune destruction of melanocytes. "The Turkish in contrast to the Han Chinese exhibited an association between 158 G/A COMT polymorphism and acrofacial vitiligo." (PMID 24915010, 2014). "The frequency of the wild and combined genotypes of the COMT 158 G/A polymorphism among vitiligo patients and the association with risk of vitiligo." (PMID 24915010, 2014). "Therefore, we evaluated the role of the 158 G/A COMT functional polymorphism in the increased risk of vitiligo in an Egyptian population." (PMID 24915010, 2014). "Since COMT takes part in the autocytotoxic/metabolic impairment of melanocytes and other epidermal cells in vitiligo, the COMT-158 G/A polymorphism might be involved in the etiology of vitiligo." (PMID 24915010, 2014). "COMT is involved in the metabolism of amine neurotransmitters such as DA, EP, and NE, and epidermal homogenates in vitiligo patients showed higher levels of COMT activity than those of healthy controls." (PMID 34360837, 2021). "In other words, epithelial homogenates of patients with vitiligo showed a higher level of COMT activity than healthy controls." (PMID 34360837, 2021). "Genotype and allele distributions of COMT 158 G/A polymorphism in vitiligo patients were not significantly different from those of controls." (PMID 24915010, 2014). "On the other hand, the 158 G/A COMT polymorphism was found to be associated with other clinical types of vitiligo in the Han Chinese but not in the Turkish." (PMID 24915010, 2014).
acne (1 paper, 2009). An inflammatory process of the sebaceous glands which is characterized by comedones, nodules, papules and/or pustules on the skin. "The activity of erythrocyte COMT showed nonsignificant changes among the obese with or without acne vis-à-vis the non obese with or without acne." (PMID 20049267, 2009).
acral melanoma (1 paper, 2022). "In our study, the COMT gene mutation was significant associated in patients with acral melanoma, which usually appear as markedly pigmented lesions, but the association with the COMT gene mutation needs further study." (PMID 36405903, 2022). "However, the COMT gene mutation showed a significant association in acral melanoma (P = 0.016), and the SLC6A4 gene mutation had a significant association in patients with TNM stage 0 or I (P = 0.008)." (PMID 36405903, 2022).
adolescent idiopathic scoliosis (1 paper, 2025). A scoliosis with no known cause arising in adolescent. "The combined impact of COMT and MTHFR on progression of adolescent idiopathic scoliosis (AIS) is unknown." (PMID 39781499, 2025).
agoraphobia (1 paper, 2023). An anxiety disorder characterized by an intense, irrational fear of venturing out into open places or situations in which help (or escape) might not be available should excessive anxiety or panic symptoms develop. "The COMT Val108/158Met genotype had an effect on the agoraphobia-related symptoms as well as on COMT DNA methylation levels." (PMID 37637902, 2023).
Akinesia (1 paper, 2022). Inability to initiate changes in activity or movement and to perform ordinary volitional movements rapidly and easily. "Morning akinesia occurred despite adjunctive treatment added to levodopa (85 % on dopamine agonists, 50 % on catechol-O-methyltransferase [COMT] inhibitors, and 92 % on monoamine oxidase-B [MAO-B] inhibitors)." (PMID 36033905, 2022).
anemia (1 paper, 2017). A reduction in the number of red blood cells, the amount of hemoglobin, and/or the volume of packed red blood cells. "The most significant results were associations between cognitive dysfunctions and genetic polymorphisms, including APOE-4 and COMT-Val; increased plasma levels of the pro-inflammatory cytokine, IL-6; anemia; and hemoglobin levels during chemotherapy." (PMID 28377717, 2017).
asthma (1 paper, 2012). "Some of these genes were altered sex specifically in the placenta of asthmatic women, including GAPDH which was only altered in males, while MDH2, COMT, and CPOX were decreased in female placentae of pregnancies complicated by asthma." (PMID 22830026, 2012). "The presence and absence of inhaled glucocorticoid use for asthma treatment during pregnancy also influenced mitochondrial gene expression, with MDH2, COMT, and CPOX gene expression being increased in placentae of females whose mothers' used these inhaled steroids during pregnancy." (PMID 22830026, 2012).
atherosclerosis (1 paper, 2018). A disease characterized by the build-up of fatty material and calcium deposition in the arterial wall resulting in partial or complete occlusion of the arterial lumen. "Moreover, genetic factors, such as Neuregulin-1 genotype and catechol-o-methyltransferase gene polymorphism, were found to have moderating effects between work stress and atherosclerosis." (PMID 29614802, 2018).
Bradycardia (1 paper, 2022). A slower than normal heart rate (in adults, slower than 60 beats per minute). "In another study, LPP amplitudes and fear-conditioned bradycardia on day 2 were elevated for CS+N compared with CS−N, but only in individuals of the Val/Val genotype of the COMT Val158Met polymorphism." (PMID 35748393, 2022).
breast adenocarcinoma (1 paper, 2013). "In this communication, we describe a cell-based system to assess estrogenic agents, which utilizes a novel competitive ELISA, based on exclusive expression of soluble-form catechol-O-methyltransferase (S-COMT) isoform in a ER-positive human breast adenocarcinoma MCF-7 cell line." (PMID 24040167, 2013).
breast tumors (1 paper, 2021). "Conversely, a significantly increased expression of COMT indicated that COMT could contribute to a putative risk in the formation of breast tumors." (PMID 34209963, 2021).
cerebral palsy (1 paper, 2018). A group of disorders affecting the development of movement and posture, often accompanied by disturbances of sensation, perception, cognition, and behavior. "The results indicated that there was a statistically significant association between a polygenic dopamine gene score reflecting the collective effects of five dopamine gene polymorphisms (COMT, DAT, DRD1, DRD2, and DRD3), and CIMT outcome in 33 children with spastic unilateral cerebral palsy." (PMID 29339100, 2018).
chronic endometritis (1 paper, 2020). A non-granulomatous or granulomatous chronic inflammation of the endometrium. "Loci rs4633 COMT and rs314280 LIN28B were significantly associated with UL through the interaction with induced abortions and chronic endometritis." (PMID 33552117, 2020).
chronic hepatitis C (1 paper, 2019). "The variant is associated with the efficacy in response to peginterferon alfa-2b in patients suffering from chronic hepatitis C. A missense variant in COMT gene (Val158Met, rs4680, PharmGKB 2A) reached the MAFSlo of 48.6%, which is in line with gnomAD MAF frequency of 46.3%." (PMID 30930780, 2019).
Dental anxiety (1 paper, 2021). "We were unable to find any statistically significant findings between pain catastrophising, A‐State, A‐Trait, Dental anxiety scores or SNPs of the COMT, NR3C1 and HTR2A genes and participants self‐reported pain levels during orthodontic treatment." (PMID 34273191, 2021).
Down syndrome (1 paper, 2024). "COMT, one of the major mammalian enzymes involved in catecholamine metabolism and degradation, with increased expression and enzymatic activity observed in Down syndrome children and model mice." (PMID 39521780, 2024).
dwarfism (1 paper, 2018). "Some of the genes in enriched ontologies are known to have direct effects on growth and size development or even dwarfism: A COMT variant increases the risk of having children with reduced birth weight, knock out of TPST2 or PATZ1 leads to growth retardation in mice." (PMID 30231878, 2018).
dyslexia (1 paper, 2018). A learning disorder characterized by an impairment in processing written words. "Interestingly, FOXP2 and COMT have been found to be associated with dyslexia and with attentional tasks in our case-control study, although these genes are not related to reading variables in the general population." (PMID 30379906, 2018). "COMT appears to be associated in the genotypic analysis to our dyslexia samples and has been connected recently to reading skill tasks (PA and spelling), as well as to reading comprehension, adding importance to the possible role of this gene in reading-related cognitive process." (PMID 30379906, 2018). "We examined 4 SNPs located on genes previously associated to dyslexia (KIAA0319, DCDC2, DYX1C1 and FOXP2) and 3 SNPs within genes related to ADHD (COMT, MAOA and DBH) in a cohort of Spanish children (N = 2078) that met the criteria of having one, both or none of these disorders (dyslexia and ADHD)." (PMID 30379906, 2018).
Erythema (1 paper, 2022). Redness of the skin, caused by hyperemia of the capillaries in the lower layers of the skin. "Incidence of erythema due a higher frequency of flushing was also found to be genotype-dependent in females (COMT G/G 44%, G/A 17% and A/A 26%, p = 0.025, medium effect size = 0.195)." (PMID 35710811, 2022).
esophageal cancer (1 paper, 2021). A primary or metastatic malignant neoplasm involving the esophagus. "Previous reports have shown that polymorphisms in COMT are responsible for the risk of esophageal cancer." (PMID 34209963, 2021).
folate deficiency (1 paper, 2023). A nutritional condition produced by a deficiency of FOLIC ACID in the diet. "COMT inhibitors may ameliorate L-dopa-induced hyper-homocysteine and folate deficiency but exacerbate vitamin B12 deficiency." (PMID 36839259, 2023).
fragile X syndrome (1 paper, 2021). A genetic syndrome caused by mutations in the FMR1 gene which is responsible for the expression of the fragile X mental retardation 1 protein. "Here, we adopt this strategy to examine relationships between three SNPs (5-HTTLPR, MAOA, COMT) and specific clinically-relevant behaviours that are phenotypic of fragile X syndrome (FXS) but vary in severity and frequency across individuals." (PMID 32862204, 2021).
fungal infections (1 paper, 2025). "In this study, we performed a comprehensive genome-wide analysis of the COMT gene family in common oat and investigated its potential role in responding to fungal infections, specifically powdery mildew and leaf spot." (PMID 40612596, 2025).
ganglioneuroma (1 paper, 2025). A benign neuroblastic tumor of the sympathetic nervous system that occurs in childhood. "We report a novel presentation of a composite PCC/ganglioneuroma that highlights the likely role of COMT in inactivating catecholamines within PCC, allowing for undetected growth of the tumour to a giant size." (PMID 41433199, 2025). "This case demonstrates a novel presentation of a composite PCC/ganglioneuroma and the presumptive role of catechol-O-methyltransferase in inactivating catecholamines within PCC, resulting in undetected growth of the tumour to a giant size." (PMID 41433199, 2025).
gastric cancer (1 paper, 2023). A primary or metastatic malignant neoplasm involving the stomach. "Additionally, polymorphisms in SHBG and catechol-O-methyltransferase, involved in estrogen inactivation, have been associated with gastric cancer risk." (PMID 37455285, 2023).
generalized anxiety disorder (1 paper, 2024). An anxiety disorder characterized by excessive and difficult-to-control worry about a number of life situations. "In this vein, a non-significant correlation in the frequency of the COMT polymorphism was found between patients with generalized anxiety disorder and HC groups, as well as between patients with different genders." (PMID 39202218, 2024).
gynecological cancers (1 paper, 2021). "As COMT polymorphisms affect enzyme capacity, the COMT gene has a significant role in estrogen metabolism and thus on hormone dependent gynecological cancers." (PMID 33389924, 2021).
Hypomagnesemia (1 paper, 2025). An abnormally decreased magnesium concentration in the blood. "In conclusion, our study revealed that SGLT2 inhibitors regulate sympathetic activity by increasing COMT activity associated with the correction of hypomagnesemia and may be involved in preventing liver fibrosis by inhibiting IL-6 production in KCs." (PMID 40715617, 2025). "In this study, we aimed to reveal the interaction between SGLT2 inhibitor-induced amelioration of hypomagnesemia and COMT activity, and those impacts on sympathetic activity." (PMID 40715617, 2025).
idiopathic scoliosis (1 paper, 2025). A scoliosis with no known cause. "Similar to our findings of MTHFR and COMT risk factors involved in AIS progression, several other studies suggest that melatonin deficiency also affects the prognosis of idiopathic scoliosis (IS), as previously stated." (PMID 39781499, 2025).